CREB1 (cAMP responsive element binding protein 1)
Diseases named in the same sentence as CREB1 in open-access papers (continued):
Sharing a sentence is not in itself a finding about the gene and the disease.
cervical carcinoma (16 papers, 2015 to 2025). A carcinoma arising from either the exocervical squamous epithelium or the endocervical glandular epithelium. "Firstly, transcriptomic analysis of HeLa (cervical cancer) cells with CREB1 deficiency or rescued CREB1 expression was carried out to identify the CREB1-mediated gene network." (PMID 34641874, 2021). "We have previously shown that the targeting of CREB1 is partially responsible for the proliferation defects observed upon miR-203 re-introduction in HPV+ cervical cancer cells." (PMID 38789663, 2024). "By analysis of public dataset (GSE39001), we found a significant higher CREB1 expression in HPV16+ cervical cancer specimens compared with healthy exocervix." (PMID 37565725, 2023). "In this study, we showed CREB1 was overexpressed in HPV+ cervical cancers and promoted cell proliferation and migration." (PMID 37565725, 2023). "To address this, we first performed wound healing assays to investigate the effect of CREB1 on the migration of cervical cancer cells." (PMID 37565725, 2023). "Going forward, as CREB1 has the potential to regulate the transcription of thousands of genes, the identification of which CREB1‐depedent genes contribute to productive infection and ultimately cervical cancer, will need to be further investigated." (PMID 37565725, 2023). "Our findings demonstrate the oncogenic function of CREB1 in HPV+ cervical cancer and its relationship with the HPV oncogenes." (PMID 37565725, 2023). "Taken together, our results suggest E6 utilizes the MAPK/MSK pathway to activate CREB1, thereby driving cervical cancer." (PMID 37565725, 2023). "Consistently, according to the OncoMine database and public dataset (GSE6791), we found significantly upregulated CREB1 expression in cervical cancers compared with normal cervical tissue." (PMID 37565725, 2023). "To circumvent this dilemma, we chose an experimentally robust cervical cancer cell line (HeLa), which has a comparable expression of CREB1 to many CREB1 sensitive cancer cell lines, to generate the CREB1 KO cells." (PMID 34641874, 2021). "Two studies so far showed that mir320a is negatively regulated by the ETS1 transcription factor and positively regulated by the CREB1 transcription factor in cervical cancer cells upon starvation." (PMID 27816966, 2016). "Here, we revealed that serum starvation induced mitophagy, altered the miRNA expression profile and increased cAMP responsive element binding protein 1 (CREB1) expression in cervical cancer cells." (PMID 26472185, 2015). "First, we transiently overexpressed CREB1 and a control vector in HeLa and C33A cervical cancer cells." (PMID 26472185, 2015). "However, few studies have focused on CREB1 in cervical cancer and especially in the context of HPV infection." (PMID 37565725, 2023). "To understand whether CREB1 plays a role in cervical cancer cell biology, we performed in vitro experiments to evaluate cell proliferation and clonogenicity in HPV+ cell lines." (PMID 37565725, 2023). "In the present study, we confirmed that CREB1 is a direct miR‐203a target in cervical cancer cells." (PMID 37565725, 2023). "Furthermore, E6‐enhanced cell proliferation in the HPV‐cervical cancer C33A cell line was at least partially CREB1‐dependent." (PMID 37565725, 2023). "However, little is known about the interplay between HPV and CREB1 activity in cervical cancer or the productive HPV lifecycle." (PMID 37565725, 2023). "Our results showed that cervical cancer cells overexpressing the miR‐203a mimic alone presented significantly suppressed cell growth and clonogenicity, whilst overexpression of CREB1 could partially rescue the suppression in HeLa and CaSKi cells." (PMID 37565725, 2023). "Our results demonstrated CREB1 overexpression could partially rescue miR‐203a‐suppressed proliferation, suggesting the importance of miR‐203a/CREB1 in regulating cervical cancer." (PMID 37565725, 2023).
cervical carcinoma (continued). "Prompt by this, we firstly generated CREB1 KO cervical cancer cells and corresponding rescue cells." (PMID 34641874, 2021). "Using RNAi knockdown and the dominant negative CREB1 inhibitor A‐CREB, we demonstrated that CREB1 functions as a proto‐oncogene by promoting proliferation, migration and EMT in HPV+ cervical cancer cells." (PMID 37565725, 2023). "Western blot analysis of a panel of cervical cancer cell lines demonstrated that CREB1 expression was upregulated in HPV16+ (CaSKi and SiHa) and HPV18+ (HeLa and SW756) transformed cervical cancer cell lines compared with primary NHK." (PMID 37565725, 2023). "Taken together, our results demonstrated that serum starvation induced CREB1 expression to activate miR-320a expression, which then suppressed VDAC1 expression to promote mitophagy, enhancing the survival of cervical cancer cells." (PMID 26472185, 2015). "We did not observe a role for CREB1 in regulating apoptosis in the cervical cancer cells, which would have provided an alternative explanation for the growth curve and clonogenicity assays undertaken." (PMID 37565725, 2023). "To understand if CREB1 plays a role in the biology of cervical cancer, we explored the TCGA database by Gene Expression Profiling Interactive Analysis (GEPIA) and found that CREB1 expression in cervical cancers was higher than normal tissue." (PMID 37565725, 2023). "The depletion of CREB1 or inhibition of CREB1 activity results in decreased cell proliferation and reduced expression of markers of epithelial to mesenchymal transition, coupled with reduced migration in HPV+ cervical cancer cell lines." (PMID 37565725, 2023). "Although CREB1 was previously reported to regulate mitophagy in cervical cancer, no investigation has been taken to study CREB1 function in the context of HPV infection, and so its functions remain to be fully elucidated in these cells." (PMID 37565725, 2023). "A previous study reported that the transcription factor cAMP responsive element binding protein 1 (CREB1) could bind to the promoter of hsa-miR-320-3p to induce its expression, which facilitated mitophagy in cervical cancer cells." (PMID 34071109, 2021). "The data showed that both CREB1 and miR-320a were upregulated in cervical cancer tissues compared to adjacent non-tumor tissues in eight of the ten specimens." (PMID 26472185, 2015). "To investigate whether this phenomenon is common among cervical cancers, we detected the expression levels of CREB1 and miR-320a in ten paired cervical cancer tissues and adjacent non-tumor tissues by qRT-PCR." (PMID 26472185, 2015).
Hypertension (16 papers, 2014 to 2025). The presence of chronic increased pressure in the systemic arterial system. "Among tissues linked to hypertension, PPP1R14D (Z = 3.12) and AMN (Z = 2.12) show maximal expression in kidney cortex, while PTMAP9 (Z = 1.16), RRAGA (Z = 1.37) and CREB1 (Z = 1.21) are most abundant in the aorta." (PMID 40909129, 2025). "According to the RGD database, both genes encoding transcription factors CREB1 and NR3C1 are associated with hypertension." (PMID 39594444, 2024).
Sepsis (15 papers, 2017 to 2025). Sepsis is defined as life-threatening organ dysfunction caused by a dysregulated host response to infection. "Moreover, DIPY markedly reduced the phosphorylation of CREB1 in LPS-challenged hAOs, LPS-induced ALI, and CLP-induced sepsis mice models." (PMID 39629132, 2024).
asthma (14 papers, 2013 to 2025). "On the other hand, phosphorylated CREB1 is known as an important activator of various genes encoding chemokines and pro-inflammatory cytokines that are biologically relevant to asthma." (PMID 30257479, 2018). "Interestingly, numerous Ca2+-dependent transcription factors like c-FOS, nuclear factor of activated T cell (NFATC1), and cAMP response element–binding protein (CREB1) as well as the asthma-associated protein ORMDL3 were downregulated in the NCLX KD HASMCs." (PMID 35841929, 2022). "CREB1 participates in promoting epigenetic changes to switch on pro-inflammatory genes and is involved in persistent bronchial inflammation in asthma and the anti-inflammatory effect of inhaled corticosteroids." (PMID 37784136, 2023). "Sec14-like 3 (Sec14l3) - a putative target of Creb1 - was down-regulated in both asthma models and in NHBE cells upon IL13 treatment, while it’s expression correlated with ciliated cell development and decreased along with increasing goblet cell metaplasia." (PMID 28383034, 2017). "Nonetheless, the family-related CREB1 protein has been widely studied in the context of asthma." (PMID 37784136, 2023). "In the case of asthma, the level of CREB1 phosphorylation in bronchial epithelium of asthmatic patients correlated with the inflammatory status, and consequently, could be used as a prognostic marker." (PMID 30257479, 2018). "Therefore, we speculate that an initial but transient dysregulation of CREB1 and CRTC-mediated transcription is sufficient to induce lasting changes of downstream targets in asthma (either directly or indirectly)." (PMID 28383034, 2017). "Thus, the role of CREB1 in asthma is not yet clear and requires further investigation." (PMID 28383034, 2017).
thyroid cancer (14 papers, 2016 to 2025). "But the fusion of CCDC6 and RET in thyroid cancer cells abrogates the ability to combine with CREB1 so as to activate CREB1." (PMID 36186907, 2022). "These authors also identified that CREB1 acts as a downstream effector of the MEX3A gene, highlighting its involvement in the regulatory pathway through which MEX3A influences thyroid cancer progression." (PMID 40722651, 2025).
colitis (13 papers, 2013 to 2025). Inflammation of the colon. "The downstream mRNAs of miR-20b-5p were further predicted and intersected, wherein CREB1 was found to be poorly-expressed in colitis." (PMID 34895044, 2021). "In our colitis mouse model, we did not observe any impact of M2-EV treatment on levels of the Meg3 and Creb1 gene in colon tissues." (PMID 37770932, 2023).
gastric adenocarcinoma (13 papers, 2005 to 2023). "According to this report, miR-182 directly targets the 3’-UTR of CREB1 mRNA and negatively regulates CREB1 mRNA and protein expression in gastric adenocarcinoma." (PMID 37438760, 2023). "They showed that the oncogene cAMP responsive element binding protein 1 (CREB1) is a target of miR-182, and that high levels of miR-182 leads to lower levels of CREB1 and suppressed gastric adenocarcinoma cell growth." (PMID 24575749, 2014). "Dysregulation of miR-182 can result in tumorigenesis, and lead to gastric adenocarcinoma through a mechanism targeted by CREB1." (PMID 23704927, 2013). "miR-182 was also found to be significantly down-regulated in human gastric adenocarcinoma tissues, and the over-expression of miR-182 would suppress the proliferation and colony formation of gastric tumours by targeting the oncogene cAMP-responsive element binding protein 1 (CREB1)." (PMID 23478435, 2013).
heart failure (13 papers, 2013 to 2025). Inability of the heart to pump blood at an adequate rate to meet tissue metabolic requirements. "CREB1 (cAMP responsive element-binding protein 1) had been implicated in the pathophysiology of heart failure." (PMID 34925046, 2021).
mesenchymal neoplasms (13 papers, 2021 to 2025). "It is a mesenchymal neoplasm characterized by fusion of a FET family member, usually EWSR1, with a member of the CREB family of transcription factors (CREB1, ATF1 or CREM)." (PMID 35266242, 2022). "Fusions between the FET gene family (EWSR1 and FUS) and one of the CREB transcription factor family members (ATF, CREB1, and CREM) have been increasingly reported in a variety of mesenchymal neoplasms that are clinically, anatomically, and phenotypically distinct." (PMID 40748380, 2025).
breast tumor (12 papers, 2011 to 2025). "If one considers all types of ERα-positive breast tumors, higher levels of CREB1 expression are significantly associated with better outcome, in this case improved “distant metastasis-free survival”." (PMID 30456355, 2018). "Notably, proximity analyses between neural markers and nuclear phospho-CREB1/ATF1 indicate that higher cancer-cell CRE activity is present in the region proximal to neural signals (NF-L, TH and SYP positive area) in breast tumors." (PMID 37463926, 2023). "There is a significant elevation in CREB1 transcript expression in breast tumor tissues compared to non-neoplastic breast tissues and this is positively associated with poor prognosis, metastatic disease and nodal involvement." (PMID 23566437, 2013). "The prognosis for ERα-negative breast tumors is not affected by CREB1 levels in this dataset." (PMID 30456355, 2018).
COVID-19 (11 papers, 2020 to 2024). A disease caused by infection with severe acute respiratory syndrome coronavirus 2. "Obvious nsp13:PRKACA and nsp13:CREB1 association signals (shown in red) were observed in COVID-19 autopsy lung tissues, as well as in mouse-adapted SARS-CoV-2-infected mouse lung tissues." (PMID 38445884, 2024). "in a study identified YY1, CREB1, and GATA2 to be critical TFs involved in the regulation of COVID-19 patients at the genetic level in their pathogenesis." (PMID 37283761, 2023). "In this work, understanding the interaction between host CREB1 and SARS-CoV-2 nsp13 may have significant implications for the development of therapeutics against COVID-19." (PMID 38445884, 2024).
liver fibrosis (11 papers, 2018 to 2025). "In contrast to these studies suggesting that CREB-1 can inhibit fibrosis, some studies indicate that it can promote hepatic fibrosis." (PMID 34805276, 2021). "Thus, our finding of predicted deactivation of the CREB1 TF upon sericin treatment aligns with the findings of previous studies suggesting that downregulation of CREB1 may contribute to the recovery of hepatic fibrosis." (PMID 38443583, 2024).
vascular dementia (11 papers, 2015 to 2025). A degenerative vascular disorder affecting the brain. "Other TFs we identified to be differentially expressed by lipid injury, such as CREB1, have also previously been implicated to play a role in vascular dementia." (PMID 32545722, 2020). "Silencing of CREB1 exasperated cognitive dysfunction in vascular dementia (VD) mouse model by inhibiting activation of the PKA-CREB signaling pathway." (PMID 35221911, 2022).
endometriosis (10 papers, 2014 to 2023). The growth of functional endometrial tissue in anatomic sites outside the uterine body. "The miR-134-5p has also been identified as a potential circulating biomarker for endometriosis, and the relationship between CREB1 and miR-134-5p has been extensively documented in the existing literature." (PMID 37947633, 2023). "Compared with normal endometrial tissues, CREB1 has a higher expression level in ectopic endometrial tissues, and it affects endometrial cell motility, growth, and invasion under endometriosis (EMS)." (PMID 37947633, 2023). "Among them, CREB1 has been reported to be closely related to endometriosis and ovarian hormone secretion, and therefore, we selected CREB1 as the object of the following research." (PMID 37947633, 2023). "NOTCH1 and CREB1 were significantly increased suggesting that the peritoneum adjacent to endometriosis lesions may be more prone to undergoing TGF-β induced EMT and neurogenesis." (PMID 25207642, 2014). "The transcription factor cAMP response element-binding protein-1 (CREB1), as an important target for multiple signaling pathways, was reported to be markedly dysregulated in endometriosis (EMS) patients." (PMID 37947633, 2023). "In humans, studies on CREB1 and ESR2 showed that they indirectly promoted the development of endometriosis." (PMID 37947633, 2023). "In recent reports, the roles of CREB1 in mediating the development of endometriosis have been noteworthy." (PMID 37947633, 2023).
alcoholism (9 papers, 2006 to 2024). "Seven nodes including JUN, FOS, RELA, MAPK1, ATF2, HRAS, and CREB1 in the backbone are the recorded genes of alcoholism, amphetamine addiction, or cocaine addiction in the KEGG pathways." (PMID 30899073, 2019). "Furthermore, our results identified the upregulation of the gene CREB1 in individuals with alcohol dependence compared to healthy controls." (PMID 39518903, 2024). "(Alcoholism, amphetamine addiction, cocaine addiction) ATF2, CREB1, CREB5, and FOSB in all three substance disease KEGG pathways are suspected be related with CREB and FOS family, and JUN." (PMID 30899073, 2019). "Moreover, ATF2, CREB1, CREB5, and FOSB in all three substance diseases (alcoholism, amphetamine, and cocaine addiction pathways)." (PMID 30899073, 2019).
diabetic nephropathy (9 papers, 2013 to 2025). "The study found important targets, including TNF, CREB1, and PTGS2, indicating that CR-C1 may be important in lowering oxidative stress and inflammation in diabetic nephropathy." (PMID 40435181, 2025).
endothelial dysfunction (9 papers, 2010 to 2023). In vascular diseases, endothelial dysfunction is a systemic pathological state of the endothelium (the inner lining of blood vessels) and can be broadly defined as an imbalance between vasodilating and vasoconstricting substances produced by (or acting on) the endothelium. "Similarly, CREB1 interacts with BAF47 (BRG1-associated factor 47) and recruits BAF47 to the proximal neogenin 1 promoter, leading to neogenin 1 trans-activation that contributes to endothelial dysfunction." (PMID 36186432, 2022).
myocardial infarction (9 papers, 2016 to 2024). Gross necrosis of the myocardium, as a result of interruption of the blood supply to the area, as in coronary thrombosis. "Downregulating the CREB1-mediated circ-HIPK3 expression level could reduce the degree of fibrosis after myocardial infarction and maintain cardiac function." (PMID 34925046, 2021). "In this study, the miR-662/CREB1/VIP regulatory pathway was successfully constructed by integrating AF and heart attack datasets." (PMID 34853624, 2021).
metabolic syndrome (8 papers, 2021 to 2025). A cluster of metabolic risk factors for CARDIOVASCULAR DISEASES and TYPE 2 DIABETES MELLITUS. "Among these, several transcription factors stand out for their close connection to cyclic AMP signaling (ATF1, ATF3, and CREB1), although their relationship to metabolic syndrome and aging is less investigated." (PMID 40011442, 2025).
metastatic tumors (8 papers, 2013 to 2023). "Since CREB1 mRNA expression predicts metastatic recurrence better than biochemical recurrence this suggests that the metastatic subgroup of PCa patients with high CREB expression have a greater risk of developing metastatic disease progression." (PMID 37573301, 2023). "Furthermore, p‐CREB1 expression was detected in another tissue microarray containing 40 pairs of primary tumors and metastatic tumor tissues, and the result showed that majority of the metastatic tumors displayed higher expression of p‐CREB1 than the matched primary tumor tissues (P < 0.05)." (PMID 32832354, 2020).
multiple myeloma (8 papers, 2014 to 2026). "The association and interaction between RSK2 and CREB1 can modulate several signaling pathways, including the toll and NF-κB pathways, in multiple myeloma cells." (PMID 37285335, 2023). "Moreover, the activation of the RSK2/CREB1 pathway is associated with multiple myeloma development by affecting cancer cell growth and survival." (PMID 37285335, 2023). "While it was known that IFN-γ via STAT1 could increase HLA-E levels, we here indisputably prove that CREB1 and STAT1 both contribute to HLA-E expression in myeloma, with CREB1 binding to HLA-E promoter and CREB1 inhibitors decreasing HLA-E expression in cell lines and patient samples." (PMID 38902472, 2024).